BDNF (brain derived neurotrophic factor)
Diseases named in the same sentence as BDNF in open-access papers (continued):
Sharing a sentence is not in itself a finding about the gene and the disease.
depression (continued). "These BDNF-levels should also play an important role in both physical activity and depression." (PMID 39670994, 2024). "Thus, although both BDNF and NfL can serve as potential markers of depression, the concept remains debatable owing to diverging research results." (PMID 38255209, 2024). "An animal study conducted in mice demonstrated that the reduction of arginase 1-positive microglia could potentially lead to anxiety/depression-like behavior through the decrease of pCREB/BDNF in Alzheimer’s Disease." (PMID 38794698, 2024). "Another review has discussed the role of zinc in regulating brain-derived neurotrophic factor (BDNF) and its impact on neural function, suggesting that the combination of zinc supplementation with antidepressants can effectively treat major depressive disorder." (PMID 39703344, 2024). "An observation from the same trial suggests that higher levels of BDNF are associated with the treatment of ayahuasca and a negative correlation between BDNF and MADRS score, suggesting yet another mechanism of how ayahuasca chemically treats depression." (PMID 38576633, 2024). "Both APOE and BDNF risk polymorphisms have been linked to a higher risk of late-life depression in non-demented older adults." (PMID 38279143, 2024). "In chronically T. cruzi-infected mice, serum BDNF levels remained unaltered, which may explain the effects of a 4-week Fx therapy, improving depression, anxiety, and memory deficits." (PMID 38776344, 2024). "A study explores the interactions between BDNF, plasticity, and depression." (PMID 39595896, 2024). "Emerging evidence suggests that reduced BDNF levels may specifically contribute to the development of depression in PD, and they potentially serve as a discriminative marker between depressed and non-depressed PD patients." (PMID 38337395, 2024). "For example, circulating levels of brain-derived neurotrophic factor (BDNF) are decreased in depression and may be altered by psychedelics." (PMID 38956594, 2024). "In another study, significantly lower BDNF plasma levels in major depressive disorder (MDD) patients who had recently attempted suicide could be shown compared to non-suicidal MDD patients and normal controls." (PMID 39194496, 2024). "The potential mechanisms of environmental pollutant-induced depression, as reported in the literature, include changes in neurotransmitters, decreased brain-derived neurotrophic factor (BDNF) levels in the hippocampus, oxidative stress, neuroinflammation, and dysfunction of various functional axes." (PMID 39771133, 2024). "This interaction between BDNF genotype and inflammation may explain why some cancer patients, particularly those undergoing chemotherapy, are more prone to depression." (PMID 39355088, 2024). "The potential of Nrf2 activation to ameliorate depression has been observed, exemplified by natural activators like resveratrol and curcumin, which demonstrated the capacity to enhance depression in animal models by modulating the expressions of BDNF and HO-1." (PMID 38180676, 2024). "Lastly, CAE was also found to significantly improve BDNF levels in patients with depression." (PMID 40226670, 2024). "The overall results indicate that α-pinene exerts its antidepressant and anxiolytic effects through 5-HT1A, β-Adrenergic, and D1 receptors while also enhancing hippocampal BDNF and dopamine synthesis, both of which are critical factors in the pathogenesis of depression and anxiety." (PMID 38318342, 2024). "Five drugs met these criteria: Topiramate in ATC N03AX (treating epilepsy, targeting GABRA4), Desipramine, Imipramine, and Nortriptyline in ATC N06AA (treating depression and anxiety, targeting BDNF) and Methylphenidate in ATC N06BA (treating ADHD, targeting DRD2)." (PMID 39070649, 2024).
depression (continued). "Additionally, analyses have shown a marked decrease in BDNF levels within the hippocampus of patients diagnosed with major depression, further underscoring the importance of BDNF in the pathophysiology of depressive conditions." (PMID 39935805, 2024). "In major depressive disorder, BDNF levels have been correlated with symptom severity, and antidepressant treatment may increase its levels." (PMID 38995015, 2024). "Brain-derived neurotrophic factor (BDNF) is a neurotrophic factor closely related to the plasticity of the nervous system, the survival of neurons, and synaptic function, playing a significant role in the pathogenesis and treatment of depression." (PMID 40226717, 2024). "Therefore, investigating BDNF and relevant signaling pathway is crucial for studying the pathogenesis of depression." (PMID 38389919, 2024). "Therefore, in addition to behavioral tests, to investigate the potential correlation between PPT and depression, we also examined the levels of BDNF, NO, IL-6, and 5-HT." (PMID 39062817, 2024). "The amount of pro‐BDNF cleavage is related to the occurrence of depression." (PMID 39639753, 2024). "Furthermore, research has shown that Lactobacillus casei can alleviate CUMS-induced depression by modulating BDNF/TrkB signaling pathways and by correcting the gut microbiota’s structural alterations." (PMID 39459643, 2024). "BDNF primarily binds to tropomyosin receptor kinase B (TrkB) receptors, facilitating neuronal differentiation and growth, and the decrease observed in depression may contribute to the reduction in hippocampal volume seen in depressed patients." (PMID 39457754, 2024). "Moreover, the chronicity of depression and the duration of the last depressive episode also appear to influence the levels of BDNF." (PMID 39408702, 2024). "Our data revealed that MGO-induced depression like-behavior and memory deficits resulted from disturbances in Trp, 5-HT, BDNF, and NGF levels, increased p-Tau and APP expression, neuroinflammation, and impaired redox status (Nrf-2/Ho-1/TXNRD1/Sirt3/5) in the brain." (PMID 39574138, 2024). "In our study, the concentration of BDNF differed significantly between depressed patients with/without suicide attempts and healthy controls which shows the association of BDNF with depression development and not suicide attempts." (PMID 39039500, 2024). "For example, DA deficiency increases the release of pro-inflammatory cytokines, which induce various processes linked to the pathophysiology of depression, including the depletion of 5-HT, DA, NE, and GABA, increased glutamate levels, and decreased BDNF-TrkB signaling." (PMID 39414710, 2024). "There are several pathophysiological hypotheses explaining depression, including the monoamine, brain-derived neurotrophic factor (BDNF), and cytokine hypotheses." (PMID 38357350, 2024). "BDNF abnormalities also contribute to astrocyte and microglial dysfunction in depression pathways." (PMID 39619203, 2024). "MMP9 may also cause a proBDNF/mBDNF (brain-derived neurotrophic factor) imbalance by influencing the process by which proBDNF is converted into mBDNF, leading to depression." (PMID 38993198, 2024). "Histone modifications further contribute to the complexity of BDNF regulation in depression: repressive histone marks like H3K27me3 have been found to accumulate in stress-sensitive brain regions, such as the hippocampus and nucleus accumbens, leading to decreased BDNF levels." (PMID 39684808, 2024). "DNA methylation of BDNF gene can be used as a biomarker for differentiating healthy controls (HCs) from patients with depression due to different methylation levels of CpG units between HCs and patients with depression (DPs)." (PMID 39130405, 2024). "An increase in BDNF decreased the odds of both depression and suicide." (PMID 39039500, 2024). "Reduced BDNF is another important factor in the pathogenesis of depression." (PMID 39844852, 2024).
depression (continued). "In mice with LPS-induced depression, quercitrin intervention could improve hippocampal damage, restore the abnormal expression of the pCREB/BDNF/PSD95/Synapsin1 pathway, regulates the PI3K/AKT/NF-κB signaling pathway, and enhances neuroplasticity." (PMID 39253375, 2024). "BDNF is significantly elevated in MIS-C patients, and it is a critical synaptic protein associated with neuronal survival, plasticity, and signaling, as well as memory, learning, depression, and anxiety." (PMID 38632526, 2024). "Consistent with our findings, studies on human adolescents investigating epigenetic changes in the BDNF gene following the experience of environmental stress, which is a well-known factor conducive to depression, reported decreased DNA methylation in the BDNF gene IV promoter." (PMID 38542252, 2024). "Similarly, BDNF, a growth factor involved in neuroinflammation, has been indicated in depression pathogenesis and antidepressant efficacy." (PMID 39055655, 2024). "Circulatory BDNF level is a molecular biomarker for anhedonia, anxiety, and depression status." (PMID 40255947, 2024). "Noteworthy, the levels of BDNF and its receptor are crucial in depression pathogenesis." (PMID 38584231, 2024). "Injection of BDNF-binding protein (TrkB-IgG) almost completely reversed the antidepressant and neuroprotective effects of vitamin D, strongly suggesting that vitamin D improved motor dysfunction and depression-like behavior in PSD model mice by promoting hippocampal BDNF signaling." (PMID 39135986, 2024). "Opposite changes in BDNF expression are observed in the brains of patients with major depression." (PMID 39619203, 2024). "In this condition, Fx may have a broader beneficial effect since recovering BDNF expression is pivotal in managing depression and memory formation." (PMID 38776344, 2024). "While evidence from preclinical studies supports the link between BDNF, depression, and the mechanisms of action of antidepressants, data from human studies remain inconclusive, limited to a few investigations with varying designs and often insufficiently large samples." (PMID 39684808, 2024). "When zinc attaches to its sensing receptors, which are GPR39, it activates the downstream cyclic MP-response element, dependent on gene transcription, resulting in high levels of brain-derived neurotrophic factor (BDNF) in specific brain regions, ultimately decreasing depression." (PMID 38690099, 2024). "In addition, findings from preclinical studies highlighted the fact that glatiramer acetate through its immunomodulatory and BDNF effects can decrease the severity of other neurological disorders such as AD and depression." (PMID 39654365, 2024). "By promoting the neuroprotective A2 phenotype and increasing BDNF expression, it may be possible to counteract the detrimental effects of chronic stress and depression on the brain’s ability to recover and achieve homeostatic regulation." (PMID 39650796, 2024). "One promising biomarker that may reveal greater insight into the relationship between sleep, depression, and rTMS is brain-derived neurotrophic factor (BDNF)." (PMID 39376965, 2024). "BDNF levels can be elevated through the use of antidepressants, structured exercise regimens, psychotherapy, and nutritional supplements like vitamin D, and omega-3 fatty acids, which support neuroplasticity and mitigate depression." (PMID 39355088, 2024). "Furthermore, rTMS has been demonstrated to raise serum BDNF levels in patients suffering from depression and sleep disorders." (PMID 39539650, 2024). "Moreover, numerous clinical studies have exposed that BDNF levels are condensed in patients with depression." (PMID 37953501, 2024). "Exercise induced BDNF could enhance the dopamine release in neuropsychiatric disorders, including Parkinson's, depression, and anxiety." (PMID 39239097, 2024).
depression (continued). "Interestingly, reduction of BDNF expression in specific forebrain regions provokes the development of depression, and upregulation of BDNF expression in these areas is mediated by the action of antidepressant agents." (PMID 37953501, 2024). "Also, multiple studies have reported that modulating the activity of BDNF decreases depressive-like behavior in animal models of depression." (PMID 39201490, 2024). "Behavioral tests indicated that mice injected with AAV‐BDNF exhibited significant relief from depression‐like phenotypes, including reduced immobility in the FST and TST and improved social interaction time and sucrose preference in BDNF‐cKO mice and TH‐Cre mice." (PMID 38155473, 2024). "Additionally, mangiferin exerts neuroprotective effects by alleviating oxidative stress levels and upregulating BDNF in the hippocampus and prefrontal cortex of mice with depression." (PMID 38915473, 2024). "Current studies suggest that depression may affect cognitive function via vascular damage, stress hormone pathway activation, and decrease in brain-derived neurotrophic factor (BDNF) and serotonin levels." (PMID 39562409, 2024). "Moreover, research has indicated that plasma BDNF levels are decreased in patients with severe depression, whereas postmortem hippocampal tissues from patients taking antidepressant drugs show increased BDNF levels." (PMID 39648800, 2024). "BDNF may contribute to the reduced hippocampal volume observed in some patients with major depression." (PMID 39767394, 2024). "Moreover, several studies suggest that physical activity improves anxiety, sleep, and mood disorders such as depression by modulation of cortisol levels and increases in Brain-Derived Neutrophic Factor (BDNF) levels." (PMID 38255692, 2024). "In addition, patients with depression showed markedly lower plasma BDNF levels than did healthy subjects." (PMID 38255209, 2024). "This indicates that PKA activation and subsequent CREB phosphorylation play a central role in regulating BDNF expression and the process of depression, emphasizing the significance of the PKA-CREB-BDNF signaling pathway in neuroprotection and antidepressant effects." (PMID 38377025, 2024). "It is also important to note that clinical studies have demonstrated a reduction in serum BDNF levels in individuals diagnosed with major depressive disorder and following the administration of antidepressant treatment, these levels have been observed to normalise." (PMID 39048810, 2024). "On the other hand, we can note that inflammation reduces neuroplasticity by downregulating brain-derived neurotrophic factor (BDNF), which may be the basis of the pathophysiology of depression." (PMID 39057075, 2024). "In light of these considerations, we conducted pairwise comparisons, network meta-analyses, and dose–response network meta-analyses to systematically evaluate and compare the effects of different exercise modalities and dosages on BDNF levels in patients with depression." (PMID 40226670, 2024). "Studies performed on the adult population have coherently demonstrated that the BDNF circulating level is significantly lower in the blood samples of depressed patients and that effective antidepressant treatment can reverse this effect, making BDNF a potential biomarker of depression and recovery." (PMID 38542252, 2024). "Furthermore, blocking BDNF abolished the antidepressant-like effects of fucoidan in mice, indicating that fucoidan ameliorates depression by inhibiting inflammation and modulating synaptic plasticity." (PMID 38812493, 2024). "Also, FSO supplementation can confer a number of health benefits in depressed women, including increased serum BDNF concentrations, along with improvements in depression status." (PMID 39056766, 2024). "Depression symptoms decreased the levels of brain-derived neurotrophic factor in a previous study." (PMID 39063657, 2024).
depression (continued). "Additionally, CREB is a transcriptional regulator that controls the expression of brain derived neurotropic factor (BDNF), a significant biomarker of depression, which is crucial for neuronal survival and function." (PMID 38315652, 2024). "Mechanistic studies have shown that pro-inflammatory cytokines promote the progression of depression by increasing oxido-nitrosative stress and impairing the expression of brain-derived neurotrophic factor (BDNF)." (PMID 39130643, 2024). "Subsequent network pharmacology and bioinformatics analysis together with experimental validation revealed that BDNF may be a key target for ZZCD in the treatment of depression." (PMID 38818577, 2024). "Additionally, BDNF plays a critical role in the clinical presentation of depression, as both peripheral and central BDNF levels are lower during depressive episodes." (PMID 39408702, 2024). "Given the critical role of impaired CREB-BDNF signaling in depression, chronic unpredictable stress may significantly increase hippocampal NR6A1 protein expression levels, decreasing hippocampal CREB phosphorylation and BDNF protein expression." (PMID 39135986, 2024). "Furthermore, variations in BDNF function appear to affect hippocampal activity in individuals with depression, suggesting that BDNF levels may serve as potential biomarkers for the early diagnosis and timely intervention for depression and associated suicidal behaviors." (PMID 39935805, 2024). "Similarly, in patients suffering from depression or in people who are suicidal, significantly decreased levels of BDNF in the brain and serum are observed when compared to the healthy population." (PMID 39201362, 2024). "BDNF has become a representative factor in depression research." (PMID 38389919, 2024). "Hence, depression is frequently diagnosed in the early stages of AD progression, and at the same time, reduced levels of both BDNF mRNA and serum BDNF levels have been described in people with depression." (PMID 39769243, 2024). "BDNF is dysregulated in different neurodegenerative diseases and depressions." (PMID 39654365, 2024). "Another study demonstrated that HIIT was more effective than MICT in enhancing BDNF, supporting our conclusion that higher-intensity exercise may have greater neurobiological benefits for patients with depression." (PMID 40226670, 2024). "This suggests that asiaticoside can regulate the gut microbiota of mice with depression-like behavior, thereby influencing the synthesis and metabolism of SCFAs and thus exerting an antidepressant effect by up-regulating the expression of 5-HT and BDNF." (PMID 39494347, 2024). "Similarly, an in vitro luciferase assay proved that BDNF is directly targeted by miR-124, and a miR-124 antagomir significantly mitigates the depression-induced reduction in BDNF levels in the rat hippocampus." (PMID 38011644, 2024). "In our study, the concentration of BDNF differed significantly between depressed patients with/without suicide attempts and healthy controls which show the association of BDNF with depression development itself and not suicide attempt." (PMID 39039500, 2024). "Few studies found that the BDNF Met allele is found more often in individuals with AD dementia with depression compared to those without depression." (PMID 38279143, 2024). "BDNF has been involved in the pathophysiology of depression in cancer patients." (PMID 39355088, 2024). "This cascade triggers the BDNF-TrkB pathway, essential for neurogenesis and synaptic regeneration, especially in the prefrontal cortex and hippocampus, regions often affected by atrophy in depression." (PMID 39769420, 2024). "In addition, the deficit of these micronutrients also decreases the expression of BDNF and iodothyronine deiodinases (DIOs), which correlates with depression and cognitive impairments (such as learning and memory) in both human and experimental animal models." (PMID 38707461, 2024).